SSRP1 (structure specific recognition protein 1)
Description:
Component of the FACT complex, a general chromatin factor that acts to reorganize nucleosomes. The FACT complex is involved in multiple processes that require DNA as a template such as mRNA elongation, DNA replication and DNA repair. During transcription elongation the FACT complex acts as a histone chaperone that both destabilizes and restores nucleosomal structure. It facilitates the passage of RNA polymerase II and transcription by promoting the dissociation of one histone H2A-H2B dimer from the nucleosome, then subsequently promotes the reestablishment of the nucleosome following the passage of RNA polymerase II. Binds specifically to double-stranded DNA and at low levels to DNA modified by the antitumor agent cisplatin. May potentiate cisplatin-induced cell death by blocking replication and repair of modified DNA. Also acts as a transcriptional coactivator for p63/TP63.
Synonyms: FACT80; FACT; T160
Tractability: PROTAC: UniProt records ubiquitination sites on it; ubiquitination databases record sites on it; its protein half-life has been measured.
Gene: Protein-coding gene on chromosome 11 (57,325,982 to 57,335,892, reverse strand). Ensembl gene ENSG00000149136.
Subcellular location: Nucleus; Nucleus, nucleolus; Chromosome
Subcellular location (Human Protein Atlas): Nucleoplasm; Centrosome; Nucleoli
Pathways (Reactome):
Disease: Formation of HIV elongation complex in the absence of HIV Tat; Formation of HIV-1 elongation complex containing HIV-1 Tat; HIV elongation arrest and recovery; Pausing and recovery of HIV elongation; Pausing and recovery of Tat-mediated HIV elongation; Tat-mediated HIV elongation arrest and recovery; Tat-mediated elongation of the HIV-1 transcript
Gene expression (Transcription): Formation of RNA Pol II elongation complex; RNA Polymerase II Pre-transcription Events; RNA Polymerase II Transcription Elongation
Chromatin organization: CHD1 and CHD2 subfamily
Gene Ontology:
Molecular function: protein binding; RNA binding; DNA binding; histone binding; nucleosome binding; chromatin binding
Biological process: nucleosome disassembly; regulation of chromatin organization; transcription elongation-coupled chromatin remodeling; nucleosome assembly
Cellular component: chromosome; FACT complex; nucleolus; nucleoplasm; nucleus
Genetic constraint (gnomAD): Loss-of-function variants: 21 observed, 88.56 expected, observed/expected ratio (o/e) 0.24, 90% interval 0.17 to 0.34. The upper end of that interval is the gene's LOEUF score, 0.34, which puts it in group 1 of 6, group 1 being the genes least tolerant of losing a copy. Missense variants: 519 observed, 944.75 expected, observed/expected ratio (o/e) 0.55, 90% interval 0.51 to 0.59. Synonymous variants: 319 observed, 336.61 expected, observed/expected ratio (o/e) 0.95, 90% interval 0.86 to 1.04.
Homologues: Orthologues: chimpanzee SSRP1 (100% identical), dog SSRP1 (99% identical), guinea pig SSRP1 (98% identical), rat Ssrp1 (98% identical), mouse Ssrp1 (98% identical), macaque SSRP1 (97% identical), pig SSRP1 (97% identical), rabbit SSRP1 (96% identical), tropical clawed frog ssrp1 (80% identical), zebrafish ssrp1b (75% identical), zebrafish ssrp1a (73% identical), Caenorhabditis elegans athp-1 (21% identical), and 1 more. Paralogues in human: UBTF (17% identical), TOX3 (11% identical), SP100 (10% identical), TOX4 (10% identical), HMGXB4 (9% identical), TOX2 (9% identical), HMGB2 (8% identical), SP140 (8% identical), HMGB1 (8% identical), TOX (8% identical), HMGB1P1 (8% identical), HMGB3 (7% identical), and 8 more.
Diseases named in the same sentence as SSRP1 in open-access papers:
SSRP1 is named in the same sentence as 42 diseases in open-access papers, as found by Europe PMC text mining. Sharing a sentence is not in itself a finding about the gene and the disease. The quoted sentences say what the papers report.
hepatocellular carcinoma (10 papers, 2020 to 2024). A malignant tumor that arises from hepatocytes. "Specifically, the high SSRP1 mRNA expression was associated with worse OS of CD8+ T cell (HR = 3.05, p < 0.01) and Treg (HR = 1.75, p < 0.01) infiltration in hepatocellular carcinoma patients." (PMID 33688504, 2021). "It has been reported that SSRP1 is highly expressed in many cancers, including colorectal cancer, prostate cancer, lung cancer, bladder cancer, breast cancer, malignant melanomas, hepatocellular carcinomas, and gliomas." (PMID 38719542, 2024). "Our results indicated that a panel of E2F target gene signature, comprising of HN1, KIF4A, CDCA3, CDCA8 and SSRP1, is a reliable tool for predicting the overall survival of Hepatocellular carcinoma patients, and provided significant reference of clinical risk for Hepatocellular carcinoma patients." (PMID 35591857, 2022).
colorectal cancer (9 papers, 2019 to 2024). A primary or metastatic malignant neoplasm that affects the colon or rectum. "In human colorectal cancer, whether SSRP1 plays a critic role and its underlying mechanisms of tumor genesis and evolution is unclear." (PMID 31839745, 2019). "Therefore, SSRP1 may providesa possible therapeutic strategy and diagnostic targets on human colorectal cancer in clinic." (PMID 31839745, 2019). "In previous studies, SSRP1 was proven to exert oncogenic function in colorectal cancer, glioma and HCC." (PMID 33407499, 2021). "Previously, miR-584-3p was confirmed to direct target Rho-associated, coiled-coil containing protein kinase 1 in glioma, matrix metallopeptidase 14 in gastric cancer, structure specific recognition protein 1 in colorectal cancer." (PMID 37305398, 2021). "Our analysis of data from TCGA confirmed that SSRP1 is upregulated in many human tumor tissues, including colorectal adenocarcinoma, along with multiple colorectal cancer cell lines." (PMID 31839745, 2019). "Collectively, these data showed that downregulation of SSRP1 inhibited colorectal cancer progression in vivo." (PMID 31839745, 2019). "In summary, the present study confirmed that SSRP1 influences the proliferation and apoptosis of colorectal cancer cells via the AKT pathway." (PMID 31839745, 2019). "In conclusion, this study demonstrated that SSRP1 silencing influenced the proliferation and apoptosis of colorectal cancer cells via the AKT signaling pathway." (PMID 31839745, 2019). "SSRP1 is suggested to play a role in the occurrence and development of tumors and thus provides a large platform for further studying the mechanisms of colorectal cancer development." (PMID 31839745, 2019). "Based on the observed effects of SSRP1 on the proliferation of colorectal cancer cells, we examined the cell cycle and apoptosis of colorectal cancer cells by flow cytometry to further explore SSRP1 regulation of colorectal cancer cell proliferation." (PMID 31839745, 2019). "Furthermore, we compared a normal colorectal cell line (NCM460) with a panel of colorectal cancer cell lines (DLD1, SW620, HCT15, HCT116, and HCT8) for SSRP1 expression and found that SSRP1 was increased in the colorectal cancer cell lines." (PMID 31839745, 2019). "We thus investigated whether the AKT signaling pathway participated in the changes in proliferation and apoptosis in colorectal cancer after SSRP1 intervention." (PMID 31839745, 2019). "To explore the function of SSRP1 in the development of colorectal cancer, we used RNAi technology to silence the expression of SSRP1 in colorectal cancer cells to observe whether SSRP1 modulation affected colorectal cancer cells." (PMID 31839745, 2019). "We demonstrated that SSRP1 knockdown via small interfering RNA significantly inhibited the proliferation of colorectal cancer cells and promoted apoptosis through the AKT signaling pathway, suppressing the invasion and migration of colorectal cancer cells in vitro and in vivo." (PMID 31839745, 2019). "Our study also verified that SSRP1 affected migration and invasion of colorectal cancer cells." (PMID 31839745, 2019). "Structure-specific recognition protein 1 (SSRP1) is involved in transcriptional regulation, DNA damage repair, and cell cycle regulation and has been confirmed to be highly expressed in various tumor tissues, including colorectal cancer." (PMID 31839745, 2019). "Since SSRP1 knockdown altered the proliferation and apoptosis of colorectal cancer in vitro as well as the migration and invasion of colorectal cancer cells, we attempted to determine whether the same phenomenon would occur in vivo." (PMID 31839745, 2019). "Therefore, this study explored the role of SSRP1 in the occurrence and development of colorectal cancer." (PMID 31839745, 2019).
colorectal cancer (continued). "Our findings and those of previous studies suggest that SSRP1 may be a target gene for cancer therapy, but further work is required to determine the potential function of SSRP1 in colorectal cancer progression." (PMID 31839745, 2019). "This indicated that SSRP1 may act as an oncogene in the development of colorectal cancer." (PMID 31839745, 2019). "Our results revealed that SSRP1 silencing activated the AKT signaling pathway to regulate proliferation, metastasis, and apoptosis in colorectal cancer." (PMID 31839745, 2019). "However, the role of SSRP1 in the development of colorectal cancer remains unclear." (PMID 31839745, 2019). "CDK1, HMGB2, SSRP1, and H2AFV may serve as key nodes for HMGB1 in colorectal cancer." (PMID 36230798, 2022). "In addition, CDK1, HMGB2, SSRP1, and H2AFV may serve as key nodes for HMGB1 in colorectal cancer." (PMID 36230798, 2022). "Significant increase of apoptotic rate and apoptosis-related protein in HCT15 cells treated with SSRP1 silence and SH-6 using western blot and flow cytometry, illustrating the inhibition of AKT signaling pathway indeed could induce apoptosis in colorectal cancer cells." (PMID 31839745, 2019).
breast carcinoma (8 papers, 2011 to 2025). "It has been shown in previous studies that SSRP1 inhibitors inhibit NF-κB-dependent transcription in breast cancer, non-small-cell lung cancer, and glioblastoma." (PMID 33688504, 2021). "Clinically, the increased expression of SSRP1 in breast cancer is related to known markers of poor prognosis." (PMID 33688504, 2021). "Among them were several nuclear proteins, which have previously been identified in BRCA1-deficient breast carcinomas (TOP1, SMC3, SSRP1 and DHX9)." (PMID 27566577, 2016). "Similar results were obtained when SSRP1 knock down effects were analyzed in the MDA-MB-231 breast cancer cells." (PMID 21679440, 2011). "In the current research, it was disclosed that SSRP1 rose in GC tissues and cells, consistent with previous studies on cancers, including NSCLC, breast cancer and liver cancer." (PMID 35291495, 2022).
glioma (8 papers, 2019 to 2024). A benign or malignant brain and spinal cord tumor that arises from glial cells (astrocytes, oligodendrocytes, ependymal cells). "Studies have consistently demonstrated that SSRP1, both at the mRNA and protein levels, is significantly elevated in glioma tissue compared to normal brain tissue." (PMID 37593751, 2023). "Knockdown of SSRP1 in vitro can suppress the proliferative capacity of glioma U251 and U87 cells by inactivating the MAPK pathway and reducing the growth of NSCLC cells." (PMID 35291495, 2022). "Collectively, these results demonstrate that the binding of pyruvate to SSRP1 promotes tumor cell survival and glioma radiation resistance." (PMID 35048565, 2022). "Downregulation of SSRP1 by siRNA technology can also inhibit the proliferation of U87 and U251 glioma cells through the MAPK pathway." (PMID 31839745, 2019). "Downregulation of SSRP1 expression by siRNA interference also results in the proliferation of U87 and U251 glioma cells through the MAPK pathway." (PMID 31839745, 2019). "It is believed that SSRP1 dramatically influences the development and occurrence of tumours, and its expression is upregulated in such tumours as hepatocellular cancer, colorectal cancer, nasopharyngeal cancer and glioma." (PMID 35291495, 2022).
gastric cancer (4 papers, 2017 to 2022). A primary or metastatic malignant neoplasm involving the stomach. "We aimed to determine the SSRP1's potential influence on the apoptosis and proliferation of gastric cancer (GC) cells and its regulatory mechanism." (PMID 35291495, 2022). "Nevertheless, the biological role and mechanism of SSRP1 in gastric cancers remain unclear." (PMID 35291495, 2022). "Validation of the RIPK genes through GEPIA identified 8 genes (NRP1, MNX1, SSRP1, PRDX2, PLRG1, LGALS4, SNX5 and FXYD3) which are highly expressed in stomach cancer were significantly down-regulated in PRU treated samples." (PMID 35831348, 2022). "Gene expression profiling using oligonucleotide arrays on 22 gastric cancer tissues revealed an increase in the expression of the genes LGALS4, FXYD3, SSRP1, and PRDX2 (Reference: GSE2685)." (PMID 35831348, 2022). "Specifically, 8 genes NRP1, MNX1, SSRP1, PRDX2, PLRG1, LGALS4, SNX5 and FXYD3) which are highly expressed in stomach cancer were significantly down-regulated in PRU treated samples." (PMID 35831348, 2022). "Specifically, 8 genes (NRP1, MNX1AS1, SSRP1, PRDX2, PLRG1, LGALS4, SNX5 and FXYD3) were found to be highly expressed in stomach cancer tissues compared to normal tissues." (PMID 35831348, 2022).
glioblastoma (4 papers, 2021 to 2024). The most malignant astrocytic tumor (WHO grade IV). "The most significant phenotype was observed for U373 cells and we further delineated the effects of RBX1, ASH2L, SSRP1 ablation on glioblastoma cell fitness using this cell line." (PMID 37974198, 2023).
liver cancer (2 papers, 2021 to 2022). An epithelial or non-epithelial malignant neoplasm that arises from the liver. "To better understand the relevance and underlying mechanisms of the SSRP1 expression in cancer, we examined the relationship between the SSRP1 expression and clinical characteristics of liver cancer patients in the Kaplan-Meier plotter database." (PMID 33688504, 2021).
lung carcinoma (2 papers, 2017 to 2024). "MiR-497 retards lung cancer cell growth or invasion by targeting CCNE1, VEGFA, whereas miR-497 does so by targeting SSRP1 in HCC." (PMID 28624790, 2017).
neuroblastoma (2 papers, 2017 to 2025). Neuroblastoma (NB) is the most common solid, extracranial childhood tumor. "In neuroblastoma, SSRP1 transcriptionally regulates N-MYC expression and pharmacological inhibition of SSRP1 using CBL0137 retarded neuroblastoma growth via N-MYC inhibition." (PMID 39706891, 2025). "There are already several examples of a functional relationship between FACT and MYC proto-oncogene, such that high enrichment of FACT over the body of the MYC gene in chromatin, feed forward interaction between FACT and NMYC in neuroblastoma and potential direct interaction of SSRP1 and c-Myc." (PMID 28423528, 2017).
ovarian carcinoma (2 papers, 2021 to 2022). A malignant neoplasm originating from the surface ovarian epithelium. "Notably, our data demonstrates that CBL0137 induces HR deficiency in SSRP1-high ovarian cancer cells." (PMID 36539830, 2022). "Since SSRP1 expression is significantly upregulated in ovarian cancer tissues compared to normal tissues, we first evaluated SSRP1 protein levels in a panel of 9 established HGSC cell lines, non-cancerous ovarian epithelial cell line HOSE17.1, and a panel of 7 HGSC patient-derived tumor cells." (PMID 36539830, 2022). "Hence, using CBL0137 in combination with carboplatin, a front-line treatment for HGSCs, may improve treatment outcomes in SSRP1-high ovarian cancer patients and deserves investigation." (PMID 36539830, 2022). "SSRP1, a component of the FAcilitates Chromatin Transcription (FACT) complex, is upregulated in ovarian carcinomas compared to normal tissue and is involved in regulation of tumor growth and DNA repair." (PMID 36539830, 2022).
rheumatoid arthritis (2 papers, 2022 to 2025). A chronic, systemic autoimmune disorder characterized by inflammation in the synovial membranes and articular surfaces. "Aberrant expression of Ssrp1, a known target of miR-211, has also been linked to rheumatoid arthritis (RA)." (PMID 40867554, 2025).
Arthritis (1 paper, 2022). Inflammation of a joint. "Lastly, we found that Ssrp1 knockdown exerts an anti-arthritis effect in CIA dKO mice by regulating proliferation and inflammation." (PMID 36511897, 2022). "Structure-specific recognition protein 1 (Ssrp1) knockdown exerts anti-arthritis effect in collagen-induced arthritis (CIA) Mir204/Mir211 double knockout (dKO) mice." (PMID 36511897, 2022).
colon cancer (1 paper, 2022). "In addition, it is reported that SSRP1 is implicated in the classical PI3K/AKT signalling pathway and affects the apoptosis and proliferation of colon cancer cells via the AKT pathway." (PMID 35291495, 2022).
colorectal adenocarcinoma (1 paper, 2019). The most common type of colorectal carcinoma. "Using bioinformatics databases, including samples from the Cancer Genome Atlas (TCGA), we confirmed high SSRP1 expression in human colorectal adenocarcinoma tissues." (PMID 31839745, 2019). "We also found that, compared with normal patients, colorectal adenocarcinoma patients showed significantly increased SSRP1 expression levels, as demonstrated by histochemical staining results from the Human Protein Atlas database." (PMID 31839745, 2019).
malignant glioma (1 paper, 2023). A grade III or grade IV glioma arising from the central nervous system. "To exemplify, suppression of SSRP1 decreases proliferation of malignant glioma through modulation of MAPK signaling." (PMID 37974198, 2023).
medulloblastoma (1 paper, 2022). A malignant, invasive embryonal neoplasm arising from the cerebellum. "Additionally, CBL0137-induced SSRP1 chromatin trapping has been shown to downregulate DNA repair pathway in MYC-high medulloblastoma cells." (PMID 36539830, 2022).
multiple myeloma (1 paper, 2026). "Moreover, Pseudokinase TRIB3 promotes multiple myeloma progression by stabilizing SSRP1 through USP10-mediated deubiquitination, thereby enhancing oncogenic signaling and tumor growth." (PMID 41522354, 2026).
nasopharyngeal carcinoma (1 paper, 2022). A carcinoma arising from the nasopharyngeal epithelium. "A previous study, in nasopharyngeal carcinoma, reported that miRNA-223 functions as a tumor suppressor, and its effects were primarily mediated via the downregulation of SSRP1 and inhibition of EMT." (PMID 36244127, 2022).
pancreatic cancers (1 paper, 2014). "In particular, SSRP1 is expressed in a high proportion of lung and pancreatic cancers (~45-59%)." (PMID 25402820, 2014).
peripheral T-cell lymphoma (1 paper, 2025). "Moreover, the SSRP1/SLC3A2 axis in arginine transport represents a novel therapeutic target to counteract immune evasion and tumor progression in peripheral T-cell lymphoma." (PMID 41208974, 2025).
viral infections (1 paper, 2025). "SSRP1 is a high mobility group box (HMG)-containing protein and subunit of the FACT histone chaperone that can also modulate viral infections." (PMID 39611842, 2025).